DAPK1 (death associated protein kinase 1)
Diseases named in the same sentence as DAPK1 in open-access papers (continued):
Sharing a sentence is not in itself a finding about the gene and the disease.
preeclampsia (2 papers, 2017 to 2022). Preeclampsia is a hypertensive disorder of pregnancy that is characterized by new-onset hypertension with proteinuria presenting after 20 weeks of gestation, and depending on mild or severe forms may initially present with severe headache, visual disturbances, and hyperreflexia. "miR-132-3p was also shown to be involved in the development of preeclampsia by promoting trophoblast cells viability and invasiveness, and inhibiting apoptosis via targeting DAPK-1." (PMID 35163786, 2022). "Immunohistochemistry of placental tissues from early-onset preeclampsia (PE) showed less DAPK1 staining, when compared to controls." (PMID 28097431, 2017). "Finally, DAPK1 expression and autophagy marker LC3B were analyzed in placental tissue and primary trophoblasts isolated from placentas complicated by early-onset preeclampsia (PE), a condition associated with increased maternal circulating pro-inflammatory cytokines." (PMID 28097431, 2017).
serous ovarian cancer (2 papers, 2025). "Emerging evidence suggests that DAPK1 downregulation may contribute to disease progression, particularly in early-stage high-grade serous ovarian cancer, though the mechanistic links remain poorly understood." (PMID 40563561, 2025). "This study aimed to investigate the role of DAPK1 in high-grade serous ovarian cancer (HGSOC) and to evaluate the therapeutic potential of restoring its kinase activity, including the use of truncated DAPK1 variants, to overcome chemoresistance and enhance tumor suppression." (PMID 40563561, 2025).
thyroid (2 papers, 2013 to 2021). "Future research is needed to elucidate the role of DAPK1 on thyroid carcinogenesis in vivo." (PMID 34831219, 2021).
adenomyoma (1 paper, 2015). A benign neoplasm characterized by the presence of a glandular and a mesenchymal (fibromyomatous) component. "Regarding the source of control samples, 10 studies evaluated DAPK1 promoter methylation in BCT from patients having gynaecological diseases such as uterine myoma, adenomyoma, and uterine prolapse, 8 studies in NT from healthy people and 2 studies in normal cervical tissues adjacent to the tumor." (PMID 26267895, 2015).
allergic asthma (1 paper, 2025). A asthma with a basis in a pathological type I hypersensitivity reaction. "This study suggests that obese patients defined by BMI may promote the development of allergic asthma by influencing the expression of plasma proteins such as TPST1, ROR1, and DAPK1." (PMID 39893495, 2025).
Allergy (1 paper, 2019). An allergy is an immune response or reaction to substances that are usually not harmful. "The findings of the current study show that the DAPK1 SNV rs1045042 is significantly associated with allergy and family history of BC, while the DAPK1 SNV rs1041326 is correlated with family history of BC and tumor differentiation." (PMID 31528229, 2019). "The DAPK1 SNV rs11141901 showed a strong association with co-morbidity (p-value = 0.002), while the rs1045042 SNV of the same gene was correlated with both allergy (p-value = 0.001) and family history of BC (p-value = 0.02)." (PMID 31528229, 2019). "Likewise, the rs11141901 and rs1041326 SNVs of the DAPK1 gene were linked with co-morbidity (p-value = 0.002) and family history of BC (p-value = 0.015), while the rs1045042 SNV of the same gene was associated with both allergy (p-value = 0.001) and family history of BC (p-value = 0.02)." (PMID 31528229, 2019).
anal squamous cell carcinoma (1 paper, 2024). A squamous cell carcinoma (SCC) arising from the anal canal or the anal margin (perianal skin). "DAPK1 is noteworthy for its specificity in anal squamous cell carcinoma and potential as a molecular biomarker." (PMID 38802881, 2024).
Babesia infection (1 paper, 2019). "Our results identified dapk-1, bi-1, gp80, and QtRibosyl genes, that have important roles in apoptosis and vitellogenesis, and demonstrated that Babesia infection fundamentally affects key processes in SG tick cells." (PMID 31001128, 2019). "The genes dapk-1, QtRibosyl, and gp80 were characterized with regard to their role on tick reproductive parameters and interaction with Babesia infection, and showed to be highly influential functional molecules." (PMID 31001128, 2019).
cardiac ischemia (1 paper, 2022). "Overexpression of miR-98 downregulated DAPK1 (death-associated protein kinase 1), leading to the attenuation of cardiac ischemia–reperfusion injury." (PMID 35246252, 2022).
colitis (1 paper, 2019). Inflammation of the colon. "Consistent with previous findings, LC3-II and DAPK1 expression were both defective in the colon of p47phox–/– mice with colitis as opposed to WT mice but restored upon treatment with Tβ4." (PMID 31719116, 2019).
COVID-19 (1 paper, 2023). A disease caused by infection with severe acute respiratory syndrome coronavirus 2. "Moreover, in addition to ribosome-related and COVID-19 pathways, neurodegeneration-related pathways were significantly enriched in the brains of DAPK1-KO mice." (PMID 37047515, 2023). "COVID-19 was the most significantly enriched KEGG pathway in the cerebral cortex, brain stem, and cerebellum, with 69, 81, and 75 related genes for DAPK1-KO males (49, 52, and 75 DEGs for DAPK1-KO females), respectively." (PMID 37047515, 2023).
dementia (1 paper, 2020). Loss of intellectual abilities interfering with an individual's social and occupational functions. "The critical role of DAPK1 in AD was confirmed at the cellular and animal levels, and it is currently believed that DAPK1 may be a key player in mediating the pathological process of dementia." (PMID 32235595, 2020).
dengue (1 paper, 2025). "We found that, MMP-2 concentrations have significantly upregulated the expression profile of apoptotic genes, that is, caspase-3, Bad, Bax, caspase-6, and DAPK-1 in lung epithelial cells suggesting its apoptosis causing property in dengue pathogenesis." (PMID 41459161, 2025).
fibroma (1 paper, 2025). A non-metastasizing neoplasm arising from the fibrous tissue. "The expression of DAPK-1 in normal epithelial tissue adjacent to fibroma biopsies is highly intense." (PMID 40104466, 2025).
follicular thyroid cancers (1 paper, 2015). "In this study, we found an association of late stage disease with DAPK1 methylation (p=0.034) in addition to an association with extra thyroidal extension (p=0.014) suggesting that DAPK1 methylation maybe a marker of advanced disease and metastasis in follicular thyroid cancers." (PMID 27158284, 2015). "Together, in this study, RASSF1, DAPK1 and ESR1 suggest utility of methylation markers to molecularly differentiate follicular thyroid cancer subtypes for enhanced classification." (PMID 27158284, 2015).
fungal infection (1 paper, 2014). "Furthermore, whether acs-3 or nhr-25 act with genes that regulate antimicrobial peptide expression specifically in response to fungal infection and epidermal damage (sta-2, snf-12, nipi-3, dapk-1), and osmotic stress (wnk-1-gck-3 signaling) needs to be determined." (PMID 24651852, 2014).
gastric adenocarcinoma (1 paper, 2016). "According to our data, methylation of the DAPK-1 promoter was more frequent in the intestinal type of gastric adenocarcinoma." (PMID 26810771, 2016). "According to our data, methylation of the DAPK-1 promoter was more frequent in intestinal-type gastric adenocarcinoma." (PMID 26810771, 2016).
Hyperglycemia (1 paper, 2022). An increased concentration of glucose in the blood. "The univariate analysis results showed age, GCS score, abnormal pupil reaction, tracheotomy, abnormal AST, hyperglycemia and the expression of DAPK1 in plasma were significantly correlated with TBI patient’s outcome." (PMID 35783103, 2022).
kidney injury (1 paper, 2025). Trauma to the kidney. "Moreover, the suppression of DAPK1 has been shown to reduce ischemic brain injury by inhibiting cell death signaling and promoting neural remodeling, which could have parallels in renal tissue, suggesting a potential for therapeutic interventions targeting DAPK1 in ischemic kidney injury." (PMID 40918124, 2025).
lentivirus infection (1 paper, 2023). Virus diseases caused by the Lentivirus genus. "Next, we constructed stably expressed knockdown DAPK1 cell lines using lentivirus infection." (PMID 37346933, 2023).
lung neoplasm (1 paper, 2020). A benign or malignant, primary or metastatic neoplasm involving the lungs. "For instance, SF(Pkinase, Death) contains seven members (MAP3K8, MAPK3, MAPK14, MAPK1, AKT1, CHEK2, and DAPK1) that are related to lung neoplasms." (PMID 31937869, 2020).
Lynch syndrome (1 paper, 2014). An autosomal dominant hereditary neoplastic syndrome characterized by the development of colorectal carcinoma and a high risk of developing endometrial carcinoma, gastric carcinoma, ovarian carcinoma, renal pelvis carcinoma, and small intestinal carcinoma.
medullary carcinoma (1 paper, 2021). "In radiation-induced medullary carcinoma in 4W rats, the expression of Cdkn2a and Cxcr4 increased, whereas that of seven autophagy regulatory genes (Dapk1, Eif2ak3, Gaa, Hgs, Mapkl4, Mapt, and Pim2) and five autophagy machinery components (Atg4b, Atg5, Gabarapl2, Rab24, and Wipi1) decreased." (PMID 34580369, 2021).
meningioma (1 paper, 2022). A generally slow growing tumor attached to the dura mater. "The different statistical analysis shows interesting interrelations between apoptotic genes and autophagy, and a surprising involvement of GSTP1, BCL2 DAPK1, and HIC1 that deserves further consideration in meningioma." (PMID 36011000, 2022).
Merkel cell carcinoma (1 paper, 2024). "Firstly, we compared the gene expression of AKT2 and DAPK1 in pan-cancer, among which Merkel cell carcinoma and Skin cutaneous melanoma (SKCM) ranked the highest AKT2 and DAPK1 expression, respectively." (PMID 38310291, 2024).
metastatic cancer (1 paper, 2024). A carcinoma which has spread from the original site of growth to another anatomic site. "Death-associated protein kinase 1 (DAPK1) is a calcium/calmodulin (Ca2+/CaM)-dependent serine/threonine (Ser/Thr) protein kinase and is characteristically downregulated in metastatic cancer." (PMID 39057063, 2024).
pancreatic adenocarcinoma (1 paper, 2011). "The relative abundance of two sense (DAPK1, MAP3K14) and one antisense-oriented (PPP3CB) intronic transcripts in samples of primary pancreatic adenocarcinoma and pancreatic metastases was independently accessed by qRT-PCR, confirming the results measured in the microarray hybridizations." (PMID 22078386, 2011).
Sepsis (1 paper, 2020). Sepsis is defined as life-threatening organ dysfunction caused by a dysregulated host response to infection. "Consistent with the data described for AKI initiated by sepsis, examination of the CLP-treated mice with DAPK1-i plus ST2825 administration identified an additive decline in Scr, BUN and lactate levels." (PMID 33052227, 2020).
synucleinopathy (1 paper, 2021). A neurodegenerative disease that is characterized by the abnormal accumulation of aggregates of alpha-synuclein protein in neurons, nerve fibers or glial cells. "MiR-26 knockdown or over-expression of DAPK1 resulted in synucleinopathy, dopaminergic neuron cell death, and motor disabilities in wild-type mice." (PMID 34422899, 2021). "In Parkinson’s disease (PD), the level of DAPK1 was increased in PD mice and positively correlated with synucleinopathy, and DAPK1 is a target of miR-26." (PMID 34422899, 2021).
transitional cell carcinoma (1 paper, 2006). A malignant neoplasm arising from the transitional epithelium, usually affecting the urinary bladder, ureter, or renal pelvis. "Transitional cell carcinoma patients had median NIM levels of 58% in the younger group and 65% in the older group for APAF-1, the corresponding levels being 16 and 10%, respectively for DAPK-1 (P=0.4 and=0.8)." (PMID 17133271, 2006).
viral infection (1 paper, 2022). "DAPK1 induces a type of noncanonical autophagy, which is induced by the upregulation of DAPK1 expression induced via viral infection, and DAPK1 directly phosphorylates Beclin1, thereby releasing it from Bcl-2." (PMID 36170016, 2022).
tumor (295 papers, 2002 to 2026). "We found that a truncated DAPK1 variant, containing the kinase domain, ankyrin repeats, and death domain (KD‐AR‐DD), retained potent tumor‐suppressive activity despite being approximately 50% shorter than the wild‐type protein." (PMID 40391786, 2025). "UV exposure inactivates Pin1 via Death-Associated Protein Kinase 1 (DAPK1), which belongs to a family of five serine/threonine kinases that possess tumor-suppressive functions and mediate a wide range of cellular processes, including apoptosis and autophagy." (PMID 41227324, 2025). "DAPK1 acts as death-associated protein kinase 1, playing an important role in tumor suppression by mediating the endoplasmic reticulum stress-dependent apoptotic pathway." (PMID 40236629, 2025). "IL-8 upregulates DAPK1 and PK expression in tumor cells, promotes lactate secretion by tumor cells and causes Treg cell infiltration." (PMID 40165895, 2025). "Death-associated protein kinase 1 (DAPK1) is a tumor suppressor gene involved in apoptosis, autophagy, and tumor progression." (PMID 40454931, 2025). "In tumour cells, overexpression of death-associated protein kinase 1 (DAPK1) mediated the disruption of the interaction between tuberous sclerosis complex proteins 1 and 2 (TSC-1/TSC-2), resulting in the activation of the mTOR pathway." (PMID 39904372, 2025). "DAPK1 also affects tumor-associated vasculature, which is an important factor in the microenvironment." (PMID 39057063, 2024). "The DAPK-1 was expressed statistically significantly lower in OL, thus signifying a relative loss of expression and a possible loss of its tumor-suppressing ability in OL lesions." (PMID 39553125, 2024). "Death associated protein kinase 1 (DAPK1), one of Ser/Thr kinase family, is an important tumor suppressor." (PMID 37666811, 2023). "Next, we analyzed how the up-regulation of uPAR in DAPK1 deficient HCT116 cells enhanced tumor cell invasion by enabling the remodeling of the surrounding ECM." (PMID 35625969, 2022). "Many studies have shown that promoter hypermethylation leads to the loss of DAPK1 expression in numerous tumor types, including chronic lymphocytic leukemia, chronic myeloid leukemia, diffuse large B-cell lymphoma, and lung cancer." (PMID 35935258, 2022). "Up-regulation of DAPK1 by grifolin can be an essential process to cause an apoptotic response in the tumor cells." (PMID 36160435, 2022). "The analysis of the expression of the DAPK1 gene (Death-Associated Protein Kinase 1), a tumor suppressor gene, mediator of programmed cell death induced by gamma-interferon, provided contradictory results." (PMID 35682732, 2022). "Our proteomics analysis added a novel network for DAPK1 loss in relation to the ECM remodeling potential of tumor cells that helps to explain the functional consequences of DAPK1 loss in tumors." (PMID 35625969, 2022). "Death-associated protein kinase 1 (DAPK1) is involved in cell cycle control, autophagy,apoptosis and tumor metastasis." (PMID 34455714, 2021). "With observations from this current study, there seems to be an association between the two where DAPK1 expression increases with increasing tumour grade." (PMID 32566040, 2020). "In contrast, DAPK1-deficient tumors showed a shift to loosely packed tumor masses and a highly infiltrative growth pattern intruding the CAM." (PMID 31772156, 2019). "We show that loss of DAPK1 implemented changes in growth pattern and enhanced tumor budding in vivo in the chorioallantoic membrane (CAM) model." (PMID 31772156, 2019). "Loss of adhesion molecule ICAM1, gain in TACSTD2 expression, and increased tumor cell–ECM interaction under DAPK1 loss seem to be central events in this process." (PMID 31772156, 2019).